FHL2 (four and a half LIM domains 2)
Diseases named in the same sentence as FHL2 in open-access papers (continued):
Sharing a sentence is not in itself a finding about the gene and the disease.
rhabdomyosarcoma (11 papers, 2009 to 2025). A rare aggressive malignant mesenchymal neoplasm arising from skeletal muscle. "Four and a half LIM domains 2 (FHL2) was originally described as ‘Down-regulated in Rhabdomyosarcoma LIM protein’ (DRAL) and is composed of LIM domains that are named after their initial discovery in the proteins Lin11, Isl-1 and Mec-3." (PMID 34685595, 2021). "FHL2 was initially discovered as one of the genes strongly down-regulated during transformation of healthy primary myoblasts into rhabdomyosarcoma tumor cells." (PMID 34685595, 2021). "Four-and-a-half LIM-only protein 2 (FHL2), also known as downregulated in rhabdomyosarcoma LIM (DRAL) domain protein, is a member of the FHL family and comprises four LIM domains and one N-terminal half LIM domain." (PMID 26320172, 2015). "FHL2 was initially identified in skeletal muscle cells and rhabdomyosarcoma." (PMID 40482916, 2025). "Originally, FHL2 has been described as “downregulated in rhabdomyosarcoma LIM protein” (DRAL)." (PMID 37834391, 2023). "FHL2 encodes a member of the four-and-a-half-LIM-only protein family which is suggested to have a role in the assembly of extracellular membranes and in transformation of normal myoblasts to rhabdomyosarcoma cells (OMIN 602633)." (PMID 28499412, 2017). "In rhabdomyosarcoma cells, FHL2 overexpression induced apoptosis." (PMID 26320172, 2015). "In contrast, FHL2 was found to be down-regulated in rhabdomyosarcomas and in prostate cancer." (PMID 23383046, 2013). "FHL2 was primarily identified as a LIM domain protein down-regulated in rhabdomyosarcomas." (PMID 19232135, 2009). "For example, in the decision rules of alveolar rhabdomyosarcoma from the LASSO algorithm, we found that the FHL2 gene targeted by the cg02563156 probe requires hypermethylation." (PMID 36619306, 2022).
osteosarcoma (10 papers, 2013 to 2025). A usually aggressive malignant bone-forming mesenchymal neoplasm, predominantly affecting adolescents and young adults. "The observed anti-apoptotic effect of FHL2 silencing in osteosarcoma cells may be linked in part to the observed decrease in Wnt5a, since this protein exerts anti-apoptotic activity in cells of the osteoblast lineage." (PMID 23383046, 2013). "It has been also associated with inhibition of breast cancer cell invasion and downregulation of four-and-a-half LIM domain protein 2 (FHL2) in human osteosarcoma cells." (PMID 38247829, 2024). "By immunohistochemistry, FHL2 is expressed in osteosarcoma samples with increased expression in metastatic and recurrent tumors compared to normal bone." (PMID 36814601, 2023). "For instance, a decrease in KLF8 expression slows down the proliferation of differentiated cells (cancerous osteoblasts) or metastases in osteosarcomas, and FHL2 positively affects osteoblastogenesis, bone formation, and bone mass." (PMID 35455019, 2022). "In summary, we show here for the first time that the expression of the Wnt co-regulator FHL2 is high in invasive osteosarcoma and that FHL2 acts as an oncoprotein in osteosarcoma cells." (PMID 23383046, 2013). "The present finding that FHL2 protein level is high in osteosarcoma tumors and correlates with osteosarcoma aggressiveness in human osteosarcoma supports a positive role of FHL2 in bone tumor development." (PMID 23383046, 2013). "FHL2 silencing also decreased the expression of c-Myc, which is involved in cell proliferation, and Wnt5a and Wnt10b, which are involved in osteosarcoma severity and invasiveness." (PMID 23383046, 2013). "More importantly, we demonstrate that silencing FHL2 represses osteosarcoma cell growth and tumorigenesis in vitro and in vivo." (PMID 23383046, 2013). "Overall, these results indicate that FHL2 silencing reduces β-catenin signaling and Wnt-responsive gene expression in murine osteosarcoma cells." (PMID 23383046, 2013). "Because the development of metastasis is highly dependent on cell migration and invasion, we investigated the impact of FHL2 silencing on the invasiveness potential of the highly metastatic K7M2 osteosarcoma cells." (PMID 23383046, 2013). "Our data indicate that FHL2 is expressed above normal in several human osteosarcoma cell lines and in the aggressive K7M2 murine osteosarcoma cells." (PMID 23383046, 2013). "Semi-quantitative analysis indicated that the FHL2 protein expression increases with tumor grade in human osteosarcoma and correlates with osteosarcoma aggressiveness." (PMID 23383046, 2013). "Our findings demonstrate that FHL2 acts as an oncogene in osteosarcoma cells and contributes to tumorigenesis through Wnt signaling." (PMID 23383046, 2013). "Strikingly, we found that FHL2 silencing reduced osteosarcoma cell invasion and migration in vitro and metastatic development in vivo." (PMID 23383046, 2013). "We next determined the consequences of FHL2 silencing on osteosarcoma cell growth and survival in basal and Wnt3a-supplemented medium." (PMID 23383046, 2013). "Our data indicate that FHL2 silencing reduces osteosarcoma cell tumorigenesis in vitro and in vivo, indicating that FHL2 is a potential target for therapeutical intervention in this type of cancer." (PMID 23383046, 2013). "We found that FHL2 silencing increased Foxo1 expression in osteosarcoma cells, suggesting a possible implication of Foxo1 in the anti-apoptotic effect of FHL2 silencing in osteosarcoma cells." (PMID 23383046, 2013). "To investigate the specific role of FHL2 in osteosarcoma tumor development, we used K7M2 murine osteosarcoma cells that express high FHL2 levels in basal conditions." (PMID 23383046, 2013).
osteosarcoma (continued). "Despite our finding that FHL2 silencing reduced osteosarcoma cell apoptosis in vitro and in vivo, we found that the overall effect of FHL2 silencing in vivo is to suppress tumor growth, indicating that FHL2 acts mostly as an oncoprotein in osteosarcoma cells." (PMID 23383046, 2013). "In murine osteosarcoma cells, FHL2 silencing using shRNA decreased canonical Wnt/β-catenin signaling and reduced the expression of Wnt responsive genes as well as of the key Wnt molecules Wnt5a and Wnt10b." (PMID 23383046, 2013). "To confirm the impact of FHL2 silencing on Wnt signaling in osteosarcoma cells, we performed a molecular analysis of Wnt responsive gene expression." (PMID 23383046, 2013). "Western blot analyses showed that FHL2 is expressed above normal in most human and murine osteosarcoma cells." (PMID 23383046, 2013). "Tissue microarray analysis revealed that FHL2 protein expression is high in human osteosarcoma and correlates with osteosarcoma aggressiveness." (PMID 23383046, 2013). "Overall, the data indicate that FHL2 is overexpressed in osteosarcoma and demonstrate that silencing FHL2 reduces Wnt signaling and decrease osteosarcoma cell growth, invasiveness and tumorigenesis in vivo." (PMID 23383046, 2013). "To determine the potential role of FHL2 in human osteosarcoma, we investigated the expression of FHL2 in tissue microarray (TMA) from patients with osteosarcoma." (PMID 23383046, 2013). "We found that FHL2 silencing reduced effector caspases activity in murine K7M2 osteosarcoma cells in basal and serum-deprived conditions." (PMID 23383046, 2013). "Furthermore, short hairpin knockdown of Fhl2 in murine K7M2 osteosarcoma cells reduced β-catenin nuclear translocation and decreased the expression of Axin2 and Wisp-1." (PMID 36814601, 2023). "Although FHL2 silencing abrogated the positive effect of Wnt3a on osteosarcoma cell growth, this effect might be explained by overall reduced proliferation since FHL2 silencing also abrogated FGF-2-induced cell proliferation." (PMID 23383046, 2013). "Because lung metastasis is a major clinical issue in osteosarcoma, we investigated whether FHL2 silencing may impact osteosarcoma cell invasiveness in mice." (PMID 23383046, 2013). "Furthermore, recurrent osteosarcoma tissues tended to exhibit the highest FHL2 level (P<0.07 vs metastatic cells)." (PMID 23383046, 2013). "Overall, the data indicate that targeting FHL2, a Wnt activator in osteosarcoma cells, may be useful for therapeutical intervention in this type of cancer." (PMID 23383046, 2013). "We also found that FHL2 silencing slightly reduced osteosarcoma cell apoptosis in vitro." (PMID 23383046, 2013). "In this study, we investigated the role of FHL2 in tumorigenesis in osteosarcoma model." (PMID 23383046, 2013). "We also analyzed the effect of FHL2 silencing on osteosarcoma cell death using TUNEL analysis." (PMID 23383046, 2013). "Overall, these results suggest a role of FHL2 in osteosarcoma tumorigenesis." (PMID 23383046, 2013). "To investigate whether FHL2 may be a molecular target in bone cancer cells we used short hairpin RNA (shRNA)-mediated inhibition of FHL2 expression in the model of K7M2 osteosarcoma cells." (PMID 23383046, 2013). "We found that silencing FHL2 though transduction with a lentivirus encoding a specific shRNA that efficiently reduced FHL2 levels in these cells, reduced cell proliferation and repressed the oncogene c-Myc, supporting a role of FHL2 in osteosarcoma cell growth." (PMID 23383046, 2013). "However, nothing is known on the role of FHL2 in osteosarcoma cell metastasis capacity." (PMID 23383046, 2013). "We next examined whether FHL2 silencing may affect osteosarcoma cell death." (PMID 23383046, 2013). "In osteosarcoma, WNT10B expression is regulated by the transcriptional co-factor FHL2 (four and a half LIM domains protein 2)." (PMID 36814601, 2023).
osteosarcoma (continued). "FHL2 protein level was slightly increased in SaOS2 cells compared to normal cells, and was robustly expressed in MG63 and U2OS osteosarcoma cells." (PMID 23383046, 2013). "To confirm this finding, we determined the expression of FHL2 in the aggressive and highly metastatic murine (K7M2) osteosarcoma cells." (PMID 23383046, 2013). "We first analyzed by Western blot the expression of the FHL2 protein in a panel of human (U2OS, HOS, SaOS2, MG63) osteosarcoma cells with distinct genotypes compared to normal human osteoblasts (IHNC)." (PMID 23383046, 2013). "Since FHL2 localizes at focal adhesions (FAs) and stress fibers (SFs) in the cell on rigid surfaces, we first checked the localization of FHL2-GFP-BirA in U2OS cells, a human osteosarcoma cell line, which were cultured on the glass surface." (PMID 40948957, 2025). "Our immunohistochemical analysis showed that FHL2 was highly expressed in osteosarcoma tumors compared to normal bone." (PMID 23383046, 2013).
cardiomyopathy (9 papers, 2013 to 2024). A disease of the heart muscle or myocardium proper. "FHL2 has been directly linked to the development of cardiomyopathies (38, –, 41), including familial DCM." (PMID 36125265, 2022). "In response to adrenergic stress however, FHL2 is upregulated, but this blunts the hypertrophic response, indicating a cardioprotective role, which is further supported by clinical cases of cardiomyopathy with loss of functional FHL2." (PMID 30742931, 2020). "It would be interesting to investigate if the interaction between nesprin-2 and FHL2 plays a role in cardiac mechanical sensing and hypertrophy and thus contributes to cardiomyopathies." (PMID 38569934, 2024). "The extent to which HOPX and FHL2 levels are down-regulated correlates with the development of cardiomyopathy in MHC-CELFΔ severe line males." (PMID 23437181, 2013). "Both alternative splicing changes and down-regulation of HOPX and FHL2 correlate with the development of overt cardiomyopathy in MHC-CELFΔ males, which exhibit partial penetrance of the phenotype." (PMID 23437181, 2013). "Furthermore, FHL2 is involved in sarcomere integrity, partly through interaction with actin and titin, and FHL2 mutations are associated with both dilated and hypertrophic cardiomyopathy, and FHL2 is thus believed to contain cardioprotective properties." (PMID 33716758, 2021). "However, several genes that have been implicated in cardiomyopathy did demonstrate large differences between normal controls and HCM patients, including ANKRD1, FHL2, and TGFB3." (PMID 32344918, 2020). "The magnitude of these physiological changes was accompanied in both HD models by reactivation of a foetal gene programme, including the up-regulation of Anp, Bnp, Fhl1 and Fhl2 and a reduction in the α- and β- isoforms of the myosin heavy chain, all typical markers of an induced cardiomyopathy." (PMID 25101683, 2014). "A few lncRNAs are located in the introns of cardiomyopathy-related genes (e.g., TTN, ACTC1, TPM1, JPH2, ANKRD1, DTNA, TMPO, and FHL2) or physically close to these genes." (PMID 32344918, 2020).
heart failure (9 papers, 2013 to 2024). Inability of the heart to pump blood at an adequate rate to meet tissue metabolic requirements. "Altered FHL2 expression in heart failure is associated with the disruption of the normal subcellular localization of phosphofructokinase 2, adenylate kinase, and creatine kinase M isoform, as well as the reduced activity of phosphofructokinase 2 and adenylate kinase." (PMID 37175670, 2023). "In a patient with familial dilated cardiomyopathy (DCM), a Gly48Ser mutation that impairs the interactions of FHL2 with the metabolic enzyme titin/connectin may lead to cardiac dysfunction and heart failure." (PMID 33932144, 2021). "Loss of FHL2 from the sarcomere has been observed in human heart failure samples, suggesting that changes in the subcellular distribution of the protein may be associated with disease development." (PMID 24219103, 2014). "Whether FHL2 downregulation is a dispensable by-product or whether the same mechanisms leading to hypertrophy and heart failure cause this concomitant downregulation is unclear." (PMID 25358972, 2014). "The recent evidence that FHL2 plays an antihypertrophic role and that its expression is reduced in human heart failure suggested that altered FHL2 expression or variants could be associated with HCM." (PMID 25358972, 2014). "Integrating the predominantly heart-specific expression of FHL2, its suggested antihypertrophic role and its lower expression in human heart failure, we hypothesized that FHL2 altered expression or genetic variants could be associated with HCM." (PMID 25358972, 2014). "Both HOPX and FHL2 are down-regulated in human heart failure, and may contribute to the dysregulation of SRF-dependent gene expression during pathogenesis." (PMID 23437181, 2013). "During heart failure, HNRNPC physically interacts with myocardial ganglion proteins FHL2, PDLIM5, and MYH7 in the heart." (PMID 38916731, 2024).
prostate carcinoma (9 papers, 2010 to 2021). A carcinoma that arises from epithelial cells of the prostate gland. "Our analysis revealed that colon and prostate cancer had similar and significantly higher levels of FHL2 expression compared to breast and non-small cell lung cancer." (PMID 34295384, 2021). "It was reported in42 that FHL2 inhibits FOXO1 activity in prostate cancer cells by promoting the deacetylation of FOXO1 through SIRT1 on DU145." (PMID 26603105, 2015). "In prostate cancer, FHL2 acts as a coactivator, shifts to the nucleus and subsequently activates FHL2- and androgen receptor-dependent genes." (PMID 23311569, 2013). "As a coactivator of AR, FHL2 in turn robustly stimulates the AR activity that is critical for prostate cancer progression." (PMID 20442768, 2010). "Although there is no report showing the direct involvement of LIM domain proteins in histone demethylation, a close correlation between the expression patterns of lysine-specific histone demethylase 1 (LSD1) and four and a half LIM-domain protein 2 (FHL2) was found in prostate cancer." (PMID 24348272, 2013). "In prostate cancer cells, FHL2 is strongly induced by androgens." (PMID 20442768, 2010).
hepatocellular carcinoma (7 papers, 2014 to 2025). A malignant tumor that arises from hepatocytes. "To achieve this, we used the well-established human hepatoma cell line HepG2 and si-pool technology for specific FHL2 suppression." (PMID 31963815, 2020). "However, FHL2 is frequently downregulated in hepatocellular carcinoma (HCC) and engages with Smad2-4 to regulate gene expression, ultimately inhibiting HCC cell proliferation." (PMID 40482916, 2025). "Recent findings showed that FHL2 is a potential tumor suppressor gene that was down-regulated in hepatocellular carcinoma (HCC)." (PMID 25121502, 2014). "In hepatocellular carcinoma cells, expression of the proteins Paired Box 5 (PAX5) and Zinc Finger Protein 5 Homolog (ZFP5) positively correlate with FHL2 expression, while potential binding sites for these proteins were found in the FHL2 promoter sequence." (PMID 34685595, 2021). "Recently, it has been shown that FHL1, FHL2, and FHL3 physically and functionally interact with Smad2, Smad3, and Smad4, important regulators of cancer development and progression, and inhibit human hepatoma cell growth in vitro and in vivo." (PMID 24690879, 2014).
ovarian carcinoma (7 papers, 2008 to 2024). A malignant neoplasm originating from the surface ovarian epithelium. "In addition, one study suggests that lower expression of miR-340-5p is associated with higher levels of FHL2 in ovarian cancer." (PMID 34295384, 2021). "Upon correlating our study's findings with the existing literature, we observed that silencing FGF8 in ovarian cancer cells resulted in the downregulation of several proteins associated with cancer progression, including SLC7A5, FHL2, SPATS2L, and DAD1." (PMID 39309198, 2024). "In one recent publication FHL2 was shown to regulate ovarian cancer cell metastasis via Wnt/β-catenin signaling." (PMID 34295384, 2021). "Among the six epithelial ovarian cancer cell lines, FHL2 had relatively higher expression levels in SKOV-3, CAOV-3 and COV-644 cells, and lower expression in IGROV-1 cells." (PMID 33092075, 2020). "Our previous study showed that FHL2 can regulate the ovarian cancer development and progression, for example, FHL2 acts as a GCT tumor cell growth-promoting factor." (PMID 33092075, 2020). "Further studies are warranted to provide more direct and systematic evidence on the role of FHL2 in the initiation and progression of epithelial ovarian cancer." (PMID 27415427, 2016). "For GSEA, we used a set of 39 genes that were down-regulated after ectopic expression of p21CIP1 in ovarian cancer cell lines, and found decreased expression in 61% of these genes in FHL2−/− MEFs." (PMID 19018287, 2008). "In ovarian cancer, miR-340 suppressed cell metastasis by targeting FHL2." (PMID 36769373, 2023). "FHL2 more highly expressed in 5 EOC cells (except IGROV-1) compared to the normal epithelial cells Hose 969, indicating that the FHL2 was highly activated in these ovarian cancer cell lines." (PMID 33092075, 2020). "Upon confirmation of the FHL2 expression profile among normal and EOC cells, we assessed the expression levels of FHL2 in 1 normal ovarian surface epithelial cells (Hose 969) and six ovarian cancer cell lines, including SKOV-3, IGROV-1, CAOV-3, CAOV-362, COV-644 and A2780." (PMID 33092075, 2020).
diabetic kidney disease (6 papers, 2015 to 2024). Progressive kidney disorder caused by vascular damage to the glomerular capillaries, in patients with diabetes mellitus. "The Lmpt mammalian ortholog is four and a half LIM domains 2 (FHL2), which has been reported to activate Wnt signaling in the pathogenesis of diabetic nephropathy." (PMID 26375667, 2015). "Other proteins found with an altered abundance in our study and known to be related to diabetic nephropathy are CTSD, FHL2, and Sec31A." (PMID 36769128, 2023).